TSLP (thymic stromal lymphopoietin)
Diseases named in the same sentence as TSLP in open-access papers (continued):
Sharing a sentence is not in itself a finding about the gene and the disease.
asthma (continued). "The efficacy of blocking TSLP in children with severe asthma remains to be seen." (PMID 28725641, 2017). "Consequently, targeting IL-25, IL-33, and TSLP is an interesting therapeutic approach for severe asthma and is actively being pursued." (PMID 28725641, 2017). "Other robust asthma associations have been found in and near IL33, TSLP, and IL1RL1, supporting the notion that epithelial cell-derived cytokines play a critical role in promoting the differentiation and activation of T helper 2 (Th2) cells in asthma pathogenesis." (PMID 28774304, 2017). "Of note, in subjects with 1 or more SPINK5 risk alleles, the absence of the TSLP protective minor alleles has been associated with a significant increase in asthma." (PMID 28583446, 2017). "Since ILC2s have been detected in airway tissues, thus we hypothesize that the augmented Th2-cytokines in nasal tissue from CRS patients with asthma may be derived from sinonasal tract ILC2s in response to enhanced IL-25, IL-33 and TSLP release." (PMID 28199345, 2017). "We investigate whether the augmented Th2-cytokines in CRS might be related to sinonasal tract ILC2s corresponding to enhanced IL-25, IL-33 and TSLP release in severe asthmatics, and be involved in asthma control." (PMID 28199345, 2017). "Interestingly, it was shown that asthma patients have increased expression of IL-25, IL-33, and TSLP in the lungs." (PMID 26965110, 2016). "We suggest that this novel model of viral-induced asthma exacerbation has translational value and is suited for in vivo studies involving pharmacological effects on exacerbation-induced expression of IL-33, TSLP and IL-25, as well as PRRs." (PMID 26879906, 2016). "TSLP is known to drive the inflammatory response in gastrointestinal diseases including celiac disease and inflammatory bowel diseas as well as allergic disorders such as asthma, atopic dermatitis, and gastrointestinal allergy." (PMID 26992000, 2016). "Furthermore, genetic variants of TSLP, IL-17RB, IL-33, and ST2 have been associated with increased susceptibility to asthma." (PMID 26965110, 2016). "Similarly, genetic studies have identified a large number of asthma susceptibility genes that are differentially expressed in the airway epithelium in asthma including interleukin 33 (IL33) and thymic stromal lymphopoietin (TSLP)." (PMID 27558999, 2016). "IL-31 is a Th2 cytokine, to determine whether its serum concentration is correlated with other asthma related Th2 cytokines in asthma, we further measured the Th2 related cytokines IL-5, IL-13 and thymic stromal lymphopoietin (TSLP)." (PMID 26956917, 2016). "That is, keratinocyte-derived IL-25, IL-33 and/or TSLP may be involved in sensitization to allergens, contributing to the development of not only atopic dermatitis but also asthma." (PMID 26230091, 2015). "In addition, we provide new evidence of the in parallel airway secretion of TSLP/CCL11/eotaxin-1 during rhinovirus-induced asthma exacerbations in children." (PMID 25546419, 2014). "Furthermore, selective inhibition of TSLP prevents allergic airway inflammation in animal models of asthma and completely ablates allergen-induced bronchoconstriction and airway eosinophilia in asthmatic subjects." (PMID 25546419, 2014). "Since TNF-alpha heightens the development of airway TSLP/Th2 pro-asthmatic responses after dsRNA exposure, our findings suggests that TNF-alpha may amplify the potential effect of TSLP in viral-induced asthma exacerbations." (PMID 25546419, 2014). "TSLP, when overexpressed by skin keratinocytes, is a systemic driver of bronchial hyperresponsiveness and its deletion prevents the atopic march from occurring, suggesting that keratinocyte-produced TSLP may be involved in the link of AD to asthma." (PMID 25419479, 2014). "TSLP is also a critical factor in airway remodeling in asthma." (PMID 24167583, 2013).
asthma (continued). "To determine whether inhibiting cytokine-induced cellular senescence can overcome airway remodeling in asthma, we explored the role of senescence in TSLP-induced airway remodeling in asthma in vitro and in vivo." (PMID 24167583, 2013). "Currently, TSLP-targeted therapies are being explored in asthma." (PMID 24167583, 2013). "Asthma is a disease with demonstrated heritability in humans, and several genes, including the IKZF3-ZPBP2-GSDMB-ORMDL3 locus, HLA-DQ, IL1RL1, IL33, TSLP, SLC22A5, SMAD3, and RORA have been consistently associated with asthma in genome-wide association studies (GWAS)." (PMID 23984888, 2013). "Here we further explored the signaling pathway in TSLP-induced airway remodeling in asthma." (PMID 24167583, 2013). "Moreover, elevated levels of IL-33, IL-25 and/or TSLP were observed in the inflamed skin of patients with atopic dermatitis, in lung smooth muscle cells and epithelial cells from patients with asthma, and/or in sera from patients with AR." (PMID 24205109, 2013). "To further explore the role of cellular senescence in airway remodeling of asthma, we tested whether TSLP, a critical cytokine in airway remodeling in asthma, induces senescence in human airway epithelial cells." (PMID 24167583, 2013). "We further demonstrated, using the chronic HDM-induced asthma model, that the inhibition of Th2 responses via neutralization of TSLP with an anti-TSLP mAb reversed airway inflammation, prevented structural alterations, and decreased AHR to methacholine and TGF-β1 level." (PMID 23300949, 2013). "TSLP may mediate its effects in part by increasing allergen uptake and processing by DCs resulting in an exacerbated asthma." (PMID 23738146, 2013). "Furthermore, we demonstrated that signaling pathway of Stat3 mediated TSLP-induced airway remodeling in asthma." (PMID 24167583, 2013). "TSLP stimulation can induce cellular senescence during airway remodeling in asthma." (PMID 24167583, 2013). "Asthma GWAS have identified a robust set of genes that are consistently associated with the disease in diverse populations (e.g. the IKZF3-ZPBP2-GSDMB-ORMDL3 locus, TSLP, and RORA), as well as genes that seem to be race/ethnicity specific (e.g. PYHIN1)." (PMID 23984888, 2013). "In asthma it was demonstrated that MC play an important role in TSLP production." (PMID 22876248, 2012). "In a separate study, mice with keratinocyte- or lung-specific overexpression of TSLP were shown to have an atopic dermatitis- or asthma-like phenotype, characterized by eosinophilia, while mice lacking the TSLP receptor have considerably attenuated disease, lacking eosinophilia." (PMID 22838633, 2012). "It is of interest that there is evidence which suggests that gender might modify the role of TSLP in asthma." (PMID 22973903, 2012). "Our findings support a role for TSLP in the pathogenesis of AR in children with asthma." (PMID 21244681, 2011). "Environmental pollutants, including tobacco smoke and diesel exhaust particles upregulate TSLP suggesting that TSLP may be an interface between environmental pollution and immune responses in asthma." (PMID 21966427, 2011). "Based on these findings, we propose that in addition to early treatment of the primary skin-barrier defects, selective inhibition of systemic TSLP may be the key to blocking the development of asthma in AD patients." (PMID 19557146, 2009). "Serum TSLP is thus an important potential therapeutic target in preventing asthma in AD patients." (PMID 19557146, 2009). "TSLP expression is enhanced by different stimuli with relevance in asthma." (PMID 18724870, 2008). "Biologic therapies for severe asthma include: anti-immunoglobulin (Ig)E (omalizumab); anti-interleukin (IL)-5 (mepolizumab and reslizumab); anti-IL-5 receptor α (IL-5Rα; benralizumab); and anti-IL-4Rα (dupilumab) and anti-thymic stromal lymphopoietin (tezepelumab)." (PMID 41458996, 2025).
asthma (continued). "TSLP and IL-33 are key players in both T2 and non-T2 inflammation, and biologics targeting these alarmins, such as tezepelumab, astegolimab, and ecaleralimab, represent promising future therapeutic options for a broader range of severe asthma patients, including those with non-T2 phenotypes." (PMID 40486460, 2025). "Thus, TSLP and IL-33 play a key role in immune hyperresponsiveness that mediates asthma attacks." (PMID 41293155, 2025). "According to reports, GSDMB may control the release of TSLP, IL-33, and IL-25, which are critical for the pathophysiology of asthma, by encouraging the infiltration of neutrophils and eosinophils in the inflamed airways; this is more pronounced in individuals with the T/C or T/T genotype." (PMID 39906448, 2025). "Hence, the increased secretion of TSLP and reduced TGFβ secretion seemed sufficient to develop a type 2 directed DC response, affecting the subsequent coculture with naïve Th cells, as generally observed in asthma allergic patients." (PMID 40046758, 2025). "Studies carried out on severe asthma have identified specific characteristics linked to the T2-prevalent “component” of the disease: the involvement of ILC2 and of cytokines called alarmins (TSLP, IL-25, IL-23), as early effectors in response to the possible epithelial damage." (PMID 40469214, 2025). "Furthermore, airway damage increases epithelial permeability, enhancing allergen exposure and promoting the release of alarmins [Interleukin-25 (IL-25), Interleukin-33 (IL-33), and thymic stromal lymphopoietin (TSLP)] by epithelial cells, which in turn induce Th2-high asthma." (PMID 40678720, 2025). "Research suggests that inhibiting TSLP with the monoclonal antibody Tezepelumab which is currently the only approved add-on treatment could benefit a wide range of asthma patients, however, limited to systemic administration methods, necessitating regular injections." (PMID 40660066, 2025). "The current biologics for severe asthma treatment include omalizumab (anti-IgE), mepolizumab and reslizumab (anti-IL-5), benralizumab (anti-IL-5 receptor), dupilumab (anti-IL-4 receptor α, blocking both the IL-4 and IL-13 pathways), and tezepelumab (anti-TSLP)." (PMID 40364184, 2025). "Although Th2 cells are at the heart of asthma pathogenesis, group 2 innate lymphoid cells (ILC2s) have gained interest in recent years because of their ability to produce type 2 cytokines and because they can be activated by the epithelial-derived alarmins IL-33, IL-25, and TSLP (left)." (PMID 41145900, 2025). "Furthermore, studies suggest that virus-induced asthma exacerbations may be associated with an impaired innate immune response to RV, especially by interferon I and III pathways, thymic stromal lymphopoietin, and the IL-33 proteins." (PMID 39507925, 2025). "However, whether TSLP can be used as a prognostic biomarker for predicting clinical remission of Th2-high pediatric asthma remains largely unexplored." (PMID 40503233, 2025). "Importantly, serum TSLP level showed significant correlations with established asthma parameters, including total IgE and key lung function indices (FEV1/FVC and FEF25-75% predicted), with multivariable regression confirming its independent association with remission (OR=1.009, P=0.023)." (PMID 40503233, 2025). "Therefore, because of its upstream strategic position, TSLP represents a suitable molecular target for add-on treatments aimed to disrupt epithelial-driven proinflammatory pathways leading to the development of severe asthma." (PMID 41321706, 2025). "Furthermore, since HMPV and RSV infection in children has been reported to drive type 2 immune responses, we analyzed the response of epithelial alarmins IL-25, IL-33, and TSLP, which play significant roles in the pathophysiology of asthma by promoting inflammation and airway hyperresponsiveness." (PMID 40143308, 2025).
asthma (continued). "Considering the role of IL-33 and the alarmin thymic stromal lymphopoietin in activating the type 2 immune response, a combined blockade of both cytokines may be beneficial in patients with immunological conditions such as asthma or CRSwNP." (PMID 39215351, 2024). "They emphasized that the occurrence of asthma may be associated not with systemic TSLP secretion but with local secretion." (PMID 38731070, 2024). "Although TSLP is one of the crucial candidate genes for the development of allergic responses and the differentiation of T cells, formal statistical analyses between the SNPs of TSLP gene and the individual susceptibility to asthma have not been demonstrated." (PMID 39118763, 2024). "Examining the TSLP genotype alone may not be sufficient for assessing the risk of developing asthma." (PMID 38731070, 2024). "The long and short forms of TSLP seem to differentially regulate IgA production, which may help explain the mechanisms behind the development and exacerbations of asthma and support the effectiveness of therapeutic interventions targeting aberrant TSLP production." (PMID 38892164, 2024). "Furthermore, HZ-1127 dramatically inhibits TSLP-dependent STAT5 activation and is more potent than Tezepelumab, which is an FDA-approved humanized mAb against TSLP for severe asthma treatment in inhibiting TSLP-induced CCL17 and CCL22 chemokines secretion in human peripheral blood mononuclear cells." (PMID 38566968, 2024). "In contrast, TSLP concentration in asthma patients induced sputum during virus-induced exacerbations was inversely related to the number of eosinophils suggesting that different mechanisms of action of TSLP could occur in acute exacerbations compared with chronic eosinophilic inflammation." (PMID 38415254, 2024). "TSLP blockade could serve as an immunomodulatory function in asthma, restoring homeostatic balance." (PMID 39483464, 2024). "While both approaches aim to modulate TSLP-mediated pathways, the direct targeting of TSLP by antibodies like HZ-1127 could offer broader therapeutic potential in diseases where TSLP plays a pivotal role, such as asthma, allergic rhinitis, and atopic dermatitis." (PMID 38566968, 2024). "Furthermore, no significant changes were observed in IL-33 levels across all GINA categories, which agrees with a recent study on TSLP and IL-33 serum levels in mild asthma patients, showing a slight reduction in sera in mild asthma compared to that in healthy controls." (PMID 38999286, 2024). "TSLP is a member of the IL-2 cytokine family and is released from airway epithelia into the bronchoalveolar fluid as part of an allergic inflammatory response and may play a role in asthma pathogenesis that is primarily T2 driven." (PMID 40980110, 2023). "T2 airway inflammation in patients with asthma, although occurring along a continuum, is characterized by a specific set of cytokines, including IL-4, IL-5, IL-13, and the so-called alarmins, IL-25 and IL-33, and thymic stromal lymphopoietin (TSLP), secreted by activated epithelial cells." (PMID 37947596, 2023). "Two single nucleotide polymorphisms (SNPs) in the TSLP promoter, rs2289276 and rs2289278, confer enhanced binding by the AP1 transcription factor and augmented lfTSLP production, explaining why these SNPs are associated with higher incidence of pediatric atopic disease and adult asthma." (PMID 37628907, 2023). "Moreover, a whole-genome sequencing association study of asthma severity in Europeans evidenced eight genome-wide significant loci previously reported as associated with asthma (IL1RL2, TSLP, HLA-DQA1, BACH2, C11orf30, RAD51B, and GSDMB) and lung function (THSD4)." (PMID 37761964, 2023). "Therefore, in this paper we aim to analyze the role of alarmins, in particular of HMGB1 and TSLP, in asthma and COPD, identifying similarities and differences which may be useful for therapeutic approaches that are as targeted as possible." (PMID 36830972, 2023).
asthma (continued). "In addition, TSLP also has convincing evidence for an effect on “Type-2-low” asthma." (PMID 37377958, 2023). "Eosinophilia can identify asthmatic patients who may benefit more significantly from ICS therapy, and monoclonal antibodies targeting IgE or the type 2 cytokines (IL‐4, IL‐5 and IL‐13) or alarmins (IL‐33, TSLP) benefit patients with the ‘Type‐2‐high’ phenotype of asthma." (PMID 37963721, 2023). "Additionally, a part of patients with high TSLP expression shows hormone resistance indicating that glucocorticoid resistance asthma might be particularly relevant to the interaction of TSLP and ILCs." (PMID 37377958, 2023). "We found that CISDs associate with the 17q21 locus (GSDMB/ZPBP2) as well as TSLP, IL33, and the gene encoding the IL33 receptor, IL1RL, which all have previously shown to be associated with asthma, and have also shown to be functionally relevant in asthma models." (PMID 36653354, 2023). "Notably, TSLP produced by keratinocytes can promote “atopic march” (the progression of atopic disorder to the onset of allergy-induced rhinitis and asthma) and aggravate allergy-induced asthma." (PMID 36983094, 2023). "Given the efficacy and safety of an anti-TSLP monoclonal antibody, tezepelumab, in a phase 3 clinical trial of severe asthma and a phase 2a clinical trial of atopic dermatitis, anti-TSLP therapy might also be a potential treatment for the development of neuropathic pain in adults." (PMID 37660072, 2023). "We were able to test our main hypothesis (differences in baseline pulmonary TSLP levels according to asthma severity in children), but it is possible that our sample size prevented us from identifying additional differences in clinical parameters or airway cytokines among our study groups." (PMID 36245744, 2022). "The anti-TSLP monoclonal antibody tezepelumab significantly reduces airway eosinophilia, and this may be the primary mechanism by which it reduces the rate of asthma exacerbations in moderate-severe asthmatics." (PMID 36237537, 2022). "Similar to the first two epithelial-derived cytokines, TSLP is also a major activator of ILC2s, which can induce the production of type 2 cytokines, and the continuous production and release of TSLP in the airway may lead to the occurrence of moderate to severe asthma that is resistant to steroids." (PMID 35744915, 2022). "Genetic polymorphisms in genes including alarmin cytokines (TSLP and IL-33) type 2 cytokines (IL-4, IL-13) and other inflammatory-related proteins (HLA, ADAM33), and vitamin D receptor have been shown to enhance, or reduce, the risk and severity of asthma in individuals." (PMID 36292755, 2022). "Interestingly, HDM challenge also markedly and significantly elevated the expression of IL-25, IL-33 and TSLP (three cytokines also thought to a play pivotal role in the initiation of asthma) in the lung tissue of both WT and Il9−/−mice compared with saline challenge." (PMID 35524325, 2022). "In addition, TSLP levels were also significantly higher in asthma groups." (PMID 36326393, 2022). "In addition, a TSLP monoclonal antibody, which targets epithelial-cell-derived cytokines, tezepelumab, could help attenuate exacerbations of asthma, but more evidence for this is needed." (PMID 36077310, 2022). "Thus, TSLP may be involved as initiator and propagator of allergic disease, such as atopic dermatitis, food allergy, and asthma, as well as cancer." (PMID 36211483, 2022). "Therefore, targeting TSLP signalling represents an intriguing therapeutic strategy in asthma." (PMID 36140430, 2022). "In addition to asthma, the epithelial-derived alarmins IL-33, IL-25, and TSLP play important roles in the pathogenesis of other allergic diseases including allergic rhinitis, chronic rhinosinusitis, atopic dermatitis, food allergy, and allergic keratoconjunctivitis." (PMID 35406669, 2022).